TLR4 (toll like receptor 4)
Diseases named in the same sentence as TLR4 in open-access papers (continued):
Sharing a sentence is not in itself a finding about the gene and the disease.
infection (continued). "Neutrophils pretreated with TAK-242 decreased the formation of NETs induced by SS2 infection, which indicated that inhibition of TLR4 signaling negatively affects SS2-induced NETs release to some degree." (PMID 30581435, 2018). "TLR4, which was up-regulated 2.6-fold in CD4+CD25+ T cells from B. bronchiseptica carriers, compared to uninfected controls, has been described to play a role in very early infection with B. bronchiseptica and to affect transmission." (PMID 30200513, 2018). "Gram-negative bacteria induced infection via lipopolysaccharide (LPS, the major constituent of the outer membrane) binding to Toll-like receptor 4 (TLR4) to produce pleiotropic inflammatory reaction." (PMID 29706995, 2018). "Furthermore, in infection with Lena as well as ILI and BOR strains, the expression of IL-8 and TLR4 was up-regulated." (PMID 29882085, 2018). "Even though TLR4 is a major sensor that detects LPS in Gram-negative bacteria, TLR4-/- mice shows increased intestinal damage compared to WT mice during STM infection." (PMID 28861073, 2017). "Further, STM infection in TLR4-/- mice displayed a significant increase in BPI expression compared to uninfected mice, but with respect to WT mice, STM mediated BPI expression is less in TLR4-/- mice." (PMID 28861073, 2017). "The donor TLR4 +3725G/G genotype resulted in one fifth of the cumulative incidence of fatal infection (0.7% vs. 4.6%; P=0.11), although there were no statistical differences." (PMID 28484092, 2017). "TLR4 is central in the inflammatory signalling cascade triggered by infection, as it constitutes the main sensor of gram‐negative bacteria, which initiates an immune reaction causing host damage." (PMID 27602552, 2017). "Upon infection with L. interrogans serovar Copenhageni strain Fiocruz L1-130, IFN-γ mRNA is expressed in the organs of mice 3 days post-infection through a TLR2- and TLR4-dependent pathway." (PMID 28270811, 2017). "Lactobacilli may contribute in the response against C. albicans colonization and infection by affecting the expression of dectin-1, TLR2, and TLR4 at the transcription level, thus altering the recognition of C. albicans and the cytokine profile of macrophages." (PMID 29238325, 2017). "After 6 h of hCFs infection with wild-type PAO1 and PA14, significant levels of TLR4, TLR5, NLRC4, native form of caspase-4 and IL-1β and IL-18 mature-formed proteins were detected by western blot with quantification of protein densitometry ratios relative to endogenous β-actin." (PMID 28469996, 2017). "This probably reflects expression of some TLRs that are triggered by EPEC PAMPs such as LPS or flagellin (e.g. TLR4, TLR5), but this signaling is inhibited by TTSS effectors upon infection with the wt EPEC, but not by the TTSS-deficient escV mutant." (PMID 28671993, 2017). "In both these tissues, TLR4 was significantly downregulated in the early (subclinical infection) as well as the late stages of infection (disease progression) when compared with non-infected controls." (PMID 27094260, 2017). "This complex is then recognized by TLR4 to induce an innate immune response to infection initiated by LPS or gram-negative bacteria." (PMID 29283389, 2017). "TLR4 is reportedly not required to control acute BCG infection, and TLR4-deficient mice display reduced bacterial clearance during long-term infection depending on the types of mutation in the common adaptor protein MyD88." (PMID 28881802, 2017). "A study performed in TLR4-positive cells (HEK 293 reporter cell lines) showed that infection with hRSV does not activate the NF-κB signaling pathway through the TLR4/MD-2/CD14 complex." (PMID 29230219, 2017). "Following E. coli-GFP infection of BMDM, TLR4 underwent endocytosis as reported by others." (PMID 29379501, 2017). "We show that in the absence of the TLR4 molecule, placental inflammation is reduced, and consequently the fetus weight was not affected by the infection." (PMID 28819109, 2017).
infection (continued). "Indeed, infection with the bacteria Klebsiella pneumoniae up-regulates TLR2 and TLR4 on the airway epithelium." (PMID 27309732, 2016). "WT and single TLR2, TLR4 and TLR9 KO mice similarly control infection in liver and spleen." (PMID 28119856, 2016). "In order to find out the role of TLR-mediated responses in the control of this pathogen, the course of infection of B. microti was analyzed over 3 weeks in wild-type (WT) and TLR knock out (KO) mice including TLR2−/−, TLR4−/−, TLR9−/−, TLR2×4−/− and TLR2×4×9−/−." (PMID 28119856, 2016). "Data from TLR4−/− LFD+I mice were not included as they showed an increased susceptibility to T. cruzi infection and so, a high mortality during the acute phase of infection." (PMID 26921251, 2016). "Also, infection with L. braziliensis significantly increased the TLR-2 and TLR4 expression on monocytes in CL patients." (PMID 26840253, 2016). "This suggests that type I IFN also plays a role in controlling bacterial growth in the absence of IFN-γR during in vivo infection with the TLR4-activating M. tuberculosis strain BTB 02-171." (PMID 27849167, 2016). "Blockade of de novo protein synthesis strongly inhibited Nos2 induction following macrophage infection with the BTB 02-171 strain, indicating that specific mediators produced upon TLR4 stimulation were required to induce Nos2 transcription in infected macrophages." (PMID 27849167, 2016). "The prototypical TLR4 agonist is represented by LPS, a cell wall component found in Gram-negative bacteria, typically encountered during an infection in soluble form." (PMID 27736941, 2016). "TLR4 activation by M. tuberculosis was found to result in the expression of host-protective factors (e.g., TNF, IFN-γ, and NOS2) and to limit bacterial growth during in vivo infection." (PMID 27849167, 2016). "After KEI 1025 infection, GLY treatment reduced HMGB1 (mRNA and protein levels) and improved disease outcome with significant reduction in mRNA levels of IL-1β, TLR4, CXCL2, and IL-12; protein expression (IL-1β, CXCL2); neutrophil infiltrate; and bacterial load." (PMID 27792814, 2016). "This evidence points to the necessity of a TLR4/CD14/MD2 complex that is activated upon detection of Gram-positive bacteria, which is now known to be responsible for rapid TNFα cytokine induction during infection." (PMID 25674081, 2015). "This could also be true in our infection model, since it has been demonstrated that cell wall components of P. brasiliensis are recognized by pattern recognition receptors such as TLR2, TLR4 and dectin-1." (PMID 26512987, 2015). "After treatment, when the infection had been controlled, the expression of TLR2 and TLR4 was still detected, and these TLRs may have been involved in the production of TNF-α, IFN-γ, IL-10 and NO, while TLR4 was involved in the production of IL-17." (PMID 25706930, 2015). "Infection of SA exposed cells did not result in the localization of TLR4 to the particle nor did TLR4 colocalize with MR." (PMID 26581716, 2015). "Moreover, transcriptional start sites (TSSs) and isoforms, as well as differential promoter usage, revealed a complex pattern of transcriptional and post-transcriptional gene regulation upon infection with TLR3 and TLR4." (PMID 26159724, 2015). "The high levels of serum IFN-γ, but not those for TNF-α during an infection with S. mansoni is dependent on ligands for TLR2 and/or TLR4, because in mice deficient for both TLRs serum IFN-γ was low throughout the infection." (PMID 25398130, 2014). "Furthermore, infection with RSV results in increased expression of TLR4 mRNA, protein, and increased TLR4 membrane localization." (PMID 24966466, 2014). "A plausible explanation is that CR3, TLR4, and TLR2, which are segregated in resting macrophages, are recruited to a single signaling platform, by as yet unknown factors, on infection with L. major." (PMID 24732131, 2014).
infection (continued). "Nevertheless, the response observed after STm is likely to be more complicated than a simple response to LPS as infection of mice lacking TLR4 resulted in a similar increase in LSK and LSK− cells to that observed in WT mice." (PMID 24825601, 2014). "TLR4 signaling, one of the strongest known inducers of NF-κB activation, seemed not activated in HSCs post-infection." (PMID 25116007, 2014). "infection, parasite subtypes capable of modulating LPS-mediated TLR-4 activation in a positive manner may disrupt this balance of basal TLR-4-dependent signals that contribute towards gut homeostasis, allowing a bystander effect of inflammation to manifest." (PMID 24551212, 2014). "Infection of TLR4−/− mice with JEV exhibited the expansion of pDC and NK cells, and enhanced JEV-specific CD4+ and CD8+ T cell responses, which are involved in viral clearance at early and late phases of infection, respectively." (PMID 25188232, 2014). "Thus, complete blocking of inflammatory responses may be negative for the proper resolution of an infection in vivo, a reasoning compatible with the observation that TLR-4-deficient animals are much less sensitive to endotoxins, while being highly prone to infections." (PMID 25047075, 2014). "We did not see any significant changes in expression of tlr2 or tlr4 two days post infection with S. Typhimurium ΔmsbB." (PMID 25423082, 2014). "At various time points after infection, higher number of CD4+ and CD8+ T cells were recruited to the lungs and MLN of WT mice compared to TLR4−/− mice, with significant differences observed from days 3 to 8 p.i. in the lungs and days 5 to 8 p.i. in the MLN compartment." (PMID 24205331, 2013). "Here, the expression of CD68, CD80, CD86, HLA-DR, MMR, TLR2 and TLR4 was analyzed under different experimental conditions (plus or minus exposure to CS, and with or without Mtb-infection)." (PMID 24278357, 2013). "TLR2 (but not TLR4) expression is increased on lung macrophages in a mouse model of infection-induced neutrophilic allergic airway disease." (PMID 23606791, 2013). "Toll-like receptor 4 was increased 18, 24, and 36 h after CASP (all versus control P = 0.0067, P = 0.0092, P = 0.0001), whereas TLR9 was elevated only 36 h after infection (versus control P = 0.0029)." (PMID 23935245, 2013). "DEFs were transiently transfected with a pcDNA3.1(+)-TLR4 expression vector and stimulated with LPS or Poly(I:C) (a dsRNA mimetic) to simulate infection with Gram-negative bacteria or viruses, respectively." (PMID 24025421, 2013). "When the macrophages are primed with LPS prior to infection, there is a moderate contribution of TRIF and IFNAR signaling to inflammasome activation, consistent with the observation that LPS stimulates the TLR4-TRIF-IFNAR axis involved in caspase-11 upregulation." (PMID 23762026, 2013). "Our results show that PPAR activation and cPLA2 inhibition significantly increased the TLR4 expression after infection compared to nontreated macrophages, indicating macrophage polarization to M1 profile." (PMID 23555077, 2013). "Moreover, the mRNA expression of TLR4 was significantly upregulated, whereas the expression of MUC2 is significantly downregulated upon infection." (PMID 24367242, 2013). "While in this study we did not evaluated the role of MyD88 in hMPV primary and secondary infection, our results indicate that TLR4 is not necessary to protect against viral challenge." (PMID 24205331, 2013). "On the contrary, Ki-67 staining even at day 19 was significantly higher than the wild type counterpart suggesting a more aggressive response to infection in the absence of functional TLR4." (PMID 24278135, 2013). "In order to determine whether this effect was specific for IAV, MDDCs were treated with agonists for the Toll-like receptors (TLR) 3, TLR4 and TLR7/8 (Poly I:C, LPS, R848 respectively) for either 4 h or 24 h prior to infection with SP." (PMID 23421931, 2013).
infection (continued). "During measurement of NF-κB activity in the crypt nuclear extracts, we did not observe any change at day 3 post-infection suggesting that absence of TLR4 apparently affected early activation of NF-κB in response to CR infection." (PMID 24278135, 2013). "Remarkably, while RAGE deficiency did not impact on total protein levels in BAL fluid, tlr4−/− mice displayed an increase of BAL fluid total protein content 6 hours after infection (P <0.01 versus Wt mice)." (PMID 24342460, 2013). "The first evidence came from the observation that TLR4 defective C3H/HeJ and C57BL/10ScCr mice are hyporesponsive to LPS and susceptible to otherwise non-lethal infection with Escherichia coli and Salmonella typhimurium." (PMID 24302927, 2013). "After day 18 post-infection, when the acquired immune responses take control, growth of Mtb strain 02-171 strain was controlled even in the absence of TLR4." (PMID 23840651, 2013). "TLR4 first recruits TRIAP and MyD88 to the site of infection." (PMID 23799152, 2013). "In contrast, the adaptive immunity was equally effective either in the presence or absence of TLR4, causing a significant reduction in CFU numbers observed after day 18 of infection." (PMID 23840651, 2013). "A lack of control in the absence of TLR2 results in enhanced infection that drives greater TLR4-mediated inflammatory responses, including maintenance of high levels of NK cells, neutrophils, DCs and T-cells." (PMID 22724018, 2012). "NF-κB was also induced as a result of infection with HSV-2 and its expression could be augmented with co-transfection of a TLR4 expression construct." (PMID 23061052, 2012). "However, upon infection with SE, three TLR mRNA were significantly up-regulated in heterophils from line A: TLR4, TLR15, and TLR21." (PMID 22783275, 2012). "Because both TLR4 and TLR2 are recruited to the infection sites during C. parvum infection of H69 cells in vitro, we cannot exclude the possibility that TLR2 also may be involved in C. parvum-induced iNOS mRNA stabilization in biliary epithelial cells." (PMID 22615562, 2012). "Although the decrease in TLR4 mRNA levels at 6 h after infection was confirmed by qRT-PCR, no significant modulation was found at a later time point, 24 h after infection (data not shown)." (PMID 22235359, 2012). "TLR4-induced hypersensitivity appears specific for a given strain, since a single ΔwaaL infection did not render mice more sensitive to subsequent instillation of NU14, 83972, or capsaicin, a known activator of bladder sensory afferents." (PMID 22899994, 2012). "Thus TLR4- and TNF-α-dependent functions, such as efficient phagocytosis and killing, appear to be sufficient to prevent lethal infection by RB50ΔsigE in Rag1−/− mice." (PMID 22897969, 2012). "The results suggest that higher susceptibility to S. enteritidis and increased bacterial load might result from depressed expression of TLR4, TLR21 and TLR2-1 at the early stage of infection." (PMID 22438967, 2012). "LPS also enhanced NO production and LVS clearance, which was not surprising, as TLR4 agonists have been shown to increase resistance to infection with F. novicida, a strain of Francisella that is virulent for mice, but rarely causes disease in humans." (PMID 22438809, 2012). "High level IL-12p40 production in ΔROP16 infection was dependent on the host cell adaptor molecule MyD88, but surprisingly was independent of any previously recognized T. gondii triggered pathway linking to MyD88 (TLR2, TLR4, TLR9, TLR11, IL-1ß and IL-18)." (PMID 21931552, 2011). "For example, genes encoding several innate immune receptors and chemokines (such as TLR4, CD83, CCL2, CXCR4, CXCL5, IL1A and IL8)—several of which participate in the initiation of a T cell response during infection —showed increased relative expression in the BTB animal group." (PMID 22182502, 2011).
infection (continued). "TLR4, the receptor to which LPS binds has been shown to participate in a variety of central nervous system insults not necessarily related to infection." (PMID 21385378, 2011). "We do not yet know if this is a direct effect of TLR4 or secondary to changes in the levels of infection/inflammation." (PMID 21513697, 2011). "Without APS stimulation, the TLR4 expression on CD4+CD25+Tregs isolated from burn plus infection mice were significantly increased on PBD7." (PMID 21698274, 2011). "This might indicate that the TLR4 signalling pathway may be less affected than the TLR7 and TLR9 signalling in Dogon undergoing infection." (PMID 21483827, 2011). "Utilizing our previously published protocol for live infection induced antigen sensitization, WT, TLR2−/−, TLR4−/−, and TRIF−/− mice were infected with 5×105 IFU of CP, sensitized with HSA for three days (beginning 5 days after infection), and then challenged with HSA." (PMID 21695198, 2011). "During infection stage that virus proteins are synthesized de novo, the host cells, such as monocytes and DCs, infected with measles virus show suppressed IL-12 production and TLR signaling, via TLR2, TLR4, TLR7, and TLR9." (PMID 20672047, 2010). "Together, these results clearly indicate that deficiency in TLR2, TLR4, TLR9 or even MyD88 expression does not impair CD8+ T cell effector responses during infection with T. cruzi." (PMID 20442858, 2010). "Thus we think that astragalus as an immunomodulator enhanced TLR4 expression and thereby increased the innate immune capability of patients with chronic UTI and promoted clearance of infection." (PMID 21151974, 2010). "Diminished TLR-4 expression has also been reported in isolated cells exposed directly to endotoxin; however, the reason for this down-regulation response during infection is not known." (PMID 20958969, 2010). "Moreover, Tbk1−/− MEF show marked defects in type I IFNs, Cxcl10, and RANTES gene expression after infection with either Sendai or Newcastle disease viruses or after engagement of the TLR3 and TLR4 by double-stranded RNA and LPS, respectively." (PMID 20090833, 2010). "LPS activates the TLR pathway (specifically, TLR4) and mimics an infection with Gram negative bacteria." (PMID 21187902, 2010). "Interestingly, the expression of Fizz-1 as a marker of alternative activation or M2 phenotype was found only in macrophages from double mutant mice, suggesting that both TLR4 and TLR9 are required to prevent alternative macrophage activation during infection." (PMID 20360853, 2010). "We conclude from these studies that TLR2 and MyD88, but not TLR4, play critical roles in the innate immune response to F. tularensis infection regardless of the route of infection or the subspecies." (PMID 19936231, 2009). "In a mouse model of infection, B. parapertussis grew rapidly in the lungs, but no measurable increase in TLR4-mediated cytokine, chemokine, or leukocyte responses were observed over the first few days of infection." (PMID 19169359, 2009). "Amplification of immune responses to infection in the kidney may also occur, as the proinflammatory cytokines TNF-α and IFN-γ have been shown to induce renal expression of Tlr2 and Tlr4." (PMID 19845042, 2009). "Surprisingly, qRT-PCR also demonstrated a small, but significant, increase in Tlr4 gene expression in response to infection by the attenuated strain that was not seen by microarray analysis." (PMID 19845042, 2009). "To determine if hepcidin could be expressed independent of TLR4 activation, we measured serum hepcidin levels in C3H/HeJ mice (TLR2+/+, TLR4-/-) and compared the values to C3H/HeSnJ mice (TLR2+/+, TLR4+/+) after infection with M. arthritidis." (PMID 19930711, 2009). "Together, these data show that in the spleen regardless of vaccination functional Tlr4 results in a higher IL-10 response after infection." (PMID 18498620, 2008).